CFTR (CF transmembrane conductance regulator)
Diseases named in the same sentence as CFTR in open-access papers (continued):
Sharing a sentence is not in itself a finding about the gene and the disease.
cystic fibrosis (continued). "In this study we developed a yeast model of gene interaction for a clinically relevant disease mutation, CFTR-ΔF508, to investigate whether it can potentially serve as a useful tool to better understand the genetic complexity underlying the human disease, cystic fibrosis." (PMID 23270647, 2012). "Cystic fibrosis is a life-limiting monogenic disorder of ion transport of exocrine glands that is caused by mutations in the CF transmembrane conductance regulator (CFTR) gene." (PMID 23209821, 2012). "The cystic fibrosis transmembrane conductance regulator (CFTR) is an epithelial chloride channel mutated in patients with cystic fibrosis." (PMID 22532795, 2012). "Cystic fibrosis is one of the most common inherited diseases and is caused by mutations in the CFTR gene." (PMID 22606534, 2012). "Cystic fibrosis is an autosomal recessive disease caused by mutations in the CFTR (Cystic Fibrosis Transmembrane Conductance Regulator) gene." (PMID 23185247, 2012). "Cystic fibrosis is caused by mutations in the gene coding for the cystic fibrosis transmembrane conductance regulator (CFTR), which functions as a plasma membrane anion channel." (PMID 23060796, 2012). "CF results from mutations and resulting dysfunction of the Cystic Fibrosis Transmembrane Conductance Regulator (CFTR)." (PMID 22822398, 2012). "CF is an inherited disorder characterized by mutation of the cystic fibrosis transmembrane regulator (CFTR), an adenosine triphosphate-dependent chloride channel that leads to exocrine gland dysfunction." (PMID 22970300, 2012). "Cystic Fibrosis is caused by ∼1,900 mutations in the CF transmembrane conductance regulator (CFTR) gene encoding for a cAMP-regulated chloride (Cl−) channel expressed in several epithelia." (PMID 23082198, 2012). "Cystic fibrosis is a recessive genetic disease that is caused by mutations to the gene encoding the cystic fibrosis transmembrane conductance regulator (CFTR) protein." (PMID 22879944, 2012). "In CF, mutations in the gene-encoding cystic fibrosis transmembrane conductance regulator (CFTR), a Cl− channel located at the apical membranes of epithelial cells, causes defective transepithelial transport of Cl− and fluid." (PMID 22514656, 2012). "The cystic fibrosis transmembrane conductance regulator (CFTR) is mutated in CF patients, and the most common mutation causes three defects in CFTR: misfolding, decreased function, and rapid degradation." (PMID 22532795, 2012). "Potentiators of cystic fibrosis transmembrane conductance regulator (CFTR) activity pharmacologically enhance CFTR function; ivacaftor is one such agent approved to treat CF patients with the G551D-CFTR gating mutation." (PMID 22768130, 2012). "CF is caused by mutations in the gene that encodes for the cystic fibrosis transmembrane conductance regulator (CFTR) protein." (PMID 22988347, 2012). "The cystic fibrosis transmembrane conductance regulator (CFTR) is a cAMP-regulated Cl- channel encoded by the gene mutated in cystic fibrosis." (PMID 21483833, 2011). "CF patients are marked by the collection of misfolded proteins in the airway epithelia due to mutations (ΔF508 and others) in the gene encoding the cystic fibrosis transmembrane conductance regulator (CFTR)." (PMID 22190939, 2011). "CF is caused by mutations in cystic fibrosis transmembrane conductance regulator (CFTR), present on the apical membranes of epithelial cells." (PMID 22410255, 2011). "The basic defect of cystic fibrosis is a deficiency in chloride secretion due to the malfunction of the Cystic Fibrosis Transmembrane Conductance Regulator (CFTR) chloride channel." (PMID 21765932, 2011). "Cystic fibrosis is an autosomal recessive disease caused by mutations in the cystic fibrosis transmembrane conductance regulator (CFTR)." (PMID 22028895, 2011).
cystic fibrosis (continued). "The genetic background is >1,500 mutations in the cystic fibrosis transmembrane conductance regulator gene (CFTR) on chromosome 7 which lead to malfunction of the chloride channel in CF patients." (PMID 21463524, 2011). "CF is caused by mutations in the gene encoding the cystic fibrosis transmembrane conductance regulator (CFTR), a multidomain ATP-binding cassette protein responsible for the regulation of transmembrane transport of chloride and other ions." (PMID 21826241, 2011). "Mechanisms leading to increased susceptibility to bacterial infections in CF are not completely known, although the involvement of cystic fibrosis transmembrane conductance regulator (CFTR) in microbicidal functions of macrophages is emerging." (PMID 21625641, 2011). "IL-8 drives the inflammatory response in cystic fibrosis which is an autosomal recessive disorder caused by mutations in the gene encoding the cystic fibrosis transmembrane conductance regulator (CFTR)." (PMID 22235381, 2011). "Cystic fibrosis is caused by mutations of the gene encoding for Cystic Fibrosis transmembrane conductance regulator (CFTR)." (PMID 22163268, 2011). "Cystic fibrosis is caused by mutations of the cystic fibrosis transmembraneconductance regulator (CFTR), a cAMP-activated anion channel conducting bothCl− and HCO3−." (PMID 21625623, 2011). "The early onset multiorgan disease cystic fibrosis is caused by more than 1,800 mutations in the CFTR gene and remains the most common fatal monogenetic disease in Caucasian populations." (PMID 21909392, 2011). "Cystic fibrosis is an autosomal recessive disease caused by mutations in the gene encoding the cystic fibrosis transmembrane conductance regulator (CFTR), a cAMP-regulated anion channel." (PMID 20843337, 2010). "In the vast majority of cystic fibrosis patients, deletion of residue F508 from CFTR is the cause of disease." (PMID 21152102, 2010). "CF is caused by a mutation in the gene coding for Cystic Fibrosis Transmembrane Regulator (CFTR) protein on chromosome 7." (PMID 27713350, 2010). "The basic defect in cystic fibrosis is caused by mutations in the epithelial chloride channel, known as the cystic fibrosis transmembrane conductance regulator (CFTR)." (PMID 20463919, 2010). "Mutations in the CFTR gene result in manifestation of cystic fibrosis, which represents the most prevalent genetic disorder in Caucasians." (PMID 22069677, 2010). "CF is an autosomal recessive disorder caused by mutations in the cystic fibrosis transmembrane conductance regulator (CFTR) gene." (PMID 21108806, 2010). "CF is caused by a mutation in the cystic fibrosis transmembrane regulator (cftr) gene leading to deficient functional capability of the CFTR transporter." (PMID 20799947, 2010). "The inflammatory milieu in the respiratory tract in cystic fibrosis has been linked to the defective expression of the cystic transmembrane regulator (CFTR) in epithelial cells." (PMID 20543983, 2010). "Mutations in the CFTR gene are known to cause cystic fibrosis, a lethal genetic disease found among Caucasian, which is characterized by defective Cl− and HCO3− secretion." (PMID 21151921, 2010). "Lung pathology in human Cystic Fibrosis and CFTR knock down animal models is characterized by chronic inflammatory changes, which preclude a single causative factor for CF." (PMID 19335897, 2009). "Cystic fibrosis is an autosomal, recessively inherited disease caused by mutations in the cystic fibrosis transmembrane conductance regulator (CFTR) gene." (PMID 19830232, 2009). "Patients with cystic fibrosis, an autosomal recessively inherited disease caused by a mutation in the Cystic Fibrosis Transmembrane Conductance Regulator (CFTR) gene, are particularly susceptible to pulmonary infections with Pseudomonas aeruginosa." (PMID 19943966, 2009).
cystic fibrosis (continued). "Cystic fibrosis is one of the most common fatal autosomal recessive disorders caused by mutations of gene for the cystic fibrosis transmembrane conductance regulator (CFTR), which is a member of the transporters acting as ATP-gated chloride channel." (PMID 19277125, 2009). "Cystic fibrosis is an autosomal recessive genetic disease caused by mutations in the CFTR (cystic fibrosis transmembrane conductance regulator) gene." (PMID 19172182, 2009). "CF is attributed to mutations in the CFTR gene, coding for the Cystic Fibrosis Transmembrane Regulator, a multifunctional transmembrane chloride channel." (PMID 19893743, 2009). "The most common mutation in CF is a deletion of phenylalanine at position 508 in the Cystic Fibrosis Transmembrane conductance Regulator protein (F508del-CFTR)." (PMID 18973672, 2008). "Cystic fibrosis is an autosomal recessive disorder caused by mutations of the CF trans-membrane regulator (CFTR) gene." (PMID 17988392, 2007). "Cystic fibrosis is the most common life-shortening genetic disease among Caucasians, being caused by mutations of the cystic fibrosis transmembrane conductance regulator (CFTR) gene." (PMID 17137500, 2006). "Cystic fibrosis is a common life-shortening genetic disorder among Caucasians caused by mutations of the cystic fibrosis transmembrane conductance regulator gene (CFTR), leading to respiratory, pancreatic, and gastro-intestinal disorders." (PMID 16438722, 2006). "CF is caused by mutations in the cystic fibrosis transmembrane conductance regulator gene (CFTR) and affects many organs, but most morbidity and mortality relates to chronic inflammation and bacterial colonisation of the lung." (PMID 16480492, 2006). "Cystic fibrosis is the most common serious, monogenic, autosomal recessive disease in Caucasians and results from mutations in the gene encoding the cystic fibrosis transmembrane conductance regulator (CFTR)." (PMID 15975149, 2005). "Cystic fibrosis is caused by mutations in the cystic fibrosis transmembrane conductance regulator (CFTR) gene." (PMID 15921521, 2005). "In a cystic fibrosis surrogate CFTR−/− mouse infection model, APR demonstrated dose dependent CFU reduction of pulmonary M. abscessus 4530, by up to 2 logs at 64 mg/kg." (PMID 41478260, 2026). "The European Cystic Fibrosis Society (ECFS) Diagnostic Network Working Group recently reported on the increased need for identification and care of seven different CFTR‐related disorders, including pancreatitis." (PMID 41536752, 2026). "These airway organoids were used to model cystic fibrosis and enable CFTR function assessment, drug screening, and host‐pathogen interaction studies." (PMID 41503026, 2026). "In this study, we quantified total and allele-specific transcript levels in nasal brushings from patients diagnosed with cystic fibrosis who are homozygous or compound heterozygous for variants in the cystic fibrosis transmembrane conductance regulator (CFTR) gene." (PMID 41760671, 2026). "Cystic fibrosis oriented studies showed that organoid swelling and electrophysiological assays correlate with CFTR functional rescue and, in selected cases, clinical response." (PMID 42278883, 2026). "IVT mRNAs have been developed to encode functional proteins such as cystic fibrosis transmembrane conductance regulator (CFTR) for cystic fibrosis or coagulation factor VIII hemophilia A." (PMID 41601966, 2026). "Cystic fibrosis transmembrane conductance regulator (CFTR) is an anion channel, and its dysfunction in CF leads to the accumulation of thick, acidic, dehydrated mucus in epithelial tissues of various organs." (PMID 41596463, 2026). "BACKGROUND: Therapy with elexacaftor/tezacaftor/ivacaftor (ETI) works to improve the functionality of the cystic fibrosis transmembrane conductance regulator (CFTR) protein and has revolutionized CF treatment." (PMID 41572264, 2026).
cystic fibrosis (continued). "Mutations in the cystic fibrosis transmembrane conductance regulator (CFTR) gene cause cystic fibrosis, a chronic, autosomal recessive disease characterized by decreased or missing CFTR protein activity which is essential for transepithelial ion transport in exocrine secreting glands." (PMID 41134303, 2026). "The physiological importance of bicarbonate efflux in the colon becomes evident in disorders such as cystic fibrosis and congenital chloride diarrhea (CLD), which arise from CFTR and DRA deficiencies, respectively." (PMID 41498431, 2026). "To elucidate the distinct physiological functions of DRA and CFTR in human large intestine, we utilized rectal organoids derived from healthy (HL) and cystic fibrosis (CF; ΔF508 homozygous) donors." (PMID 41498431, 2026). "Cystic fibrosis currently impacts nearly 40,000 individuals in the United States and is classified as a condition resulting from impairment of the cystic fibrosis transmembrane conductance regulator (CFTR) protein." (PMID 41536752, 2026). "Background/Objectives: Individual responses to CFTR modulators vary widely among people with cystic fibrosis (pwCF), underscoring the need for functional approaches that provide biological context alongside genotype-based therapy selection." (PMID 41590543, 2026). "The ABCC subfamily includes 12 genes, among which are ABCC6 and ABCC7 (CFTR, linked to cystic fibrosis), along with a pseudogene (ABCC13)." (PMID 40725385, 2025). "CF is an autosomal recessive genetic disorder caused by the absence, reduction, or impaired function of the cystic fibrosis transmembrane conductance regulator (CFTR) protein." (PMID 40426494, 2025). "Cystic Fibrosis is a fatal hereditary condition brought on by some variations in the Cystic Fibrosis Transmembrane Regulator (CFTR) gene." (PMID 40700450, 2025). "CFTR modulators have transformed cystic fibrosis management by enhancing protein function for specific mutations, leading to improved lung function and quality of life." (PMID 40282362, 2025). "CFTR is a cAMP‐activated anion channel abundantly expressed in epithelial cells, mutations (e.g., DF508) of which result in cystic fibrosis, a genetic disease commonly seen in Caucasians." (PMID 39887939, 2025). "In phase 2 trials in people with cystic fibrosis aged 18 years and older, vanzacaftor–tezacaftor–deutivacaftor has been shown to be a safe and effective, once-daily cystic fibrosis transmembrane conductance regulator (CFTR) modulator." (PMID 39756425, 2025). "Highly effective CFTR modulator regimens capable of restoring CFTR function to the normal range are a major advancement for the treatment of cystic fibrosis." (PMID 39756425, 2025). "Cystic fibrosis treatment has evolved significantly with the development of CFTR modulators, particularly elexacaftor/tezacaftor/ivacaftor (ETI)." (PMID 40553696, 2025). "Correctors like bamocaftor enhance the amount of functional CFTR protein at the cell surface, contributing to improved chloride ion transport and alleviation of cystic fibrosis symptoms." (PMID 40700450, 2025). "A mutation in the cystic fibrosis transmembrane conductance regulator (CFTR) gene results in the malfunction of the CFTR protein, which in turn causes cystic fibrosis." (PMID 40867576, 2025). "The cystic fibrosis transmembrane conductance regulator (CFTR) is an anion channel that is dysfunctional in individuals with cystic fibrosis." (PMID 39859187, 2025). "Cystic fibrosis is a genetic disorder affecting ~100,000 patients worldwide that is caused by mutations that impair the expression and/or function of a chloride channel known as the Cystic Fibrosis Transmembrane Conductance Regulator (CFTR)." (PMID 41379933, 2025). "Ensifentrine has been shown to elevate cAMP levels in human neutrophils and in isogenic human cystic fibrosis bronchial epithelial cells expressing wt-CFTR (CFBE41o-WT), indicating its ability to inhibit PDE3 and PDE4 to promote airway relaxation." (PMID 40978741, 2025).
cystic fibrosis (continued). "Patient-derived airway cell cultures are used in personalized medicine strategies for people with cystic fibrosis (pwCF) to predict potential clinical response to cystic fibrosis transmembrane conductance regulator (CFTR) modulator drugs." (PMID 40978488, 2025). "The management of pulmonary infections in cystic fibrosis remains a complex clinical challenge, despite recent therapeutic advances targeting CFTR dysfunction." (PMID 40732035, 2025). "Cystic fibrosis pharmacological correctors improvethe cysticfibrosis transmembrane conductance regulator (CFTR) protein traffickingand function." (PMID 40539870, 2025). "The most recent formulation for cystic fibrosis combines ivacaftor with another folding corrector, elexacaftor, and a channel potentiator, tezacaftor, and has shown efficacy toward CFTR mutants found in over 90% of cystic fibrosis patients." (PMID 40113044, 2025). "Cystic fibrosis is a genetic disorder caused by mutations in the Cystic Fibrosis Transmembrane Conductance Regulator (CFTR) protein, an anion channel in the apical membrane of epithelial cells that primarily affects the respiratory and digestive systems; however, its impact extends to muscle health." (PMID 41440516, 2025). "Cystic fibrosis is an autosomal recessive disorder caused by mutations in the CF transmembrane conductance regulator (CFTR) gene, encoding a chloride and bicarbonate channel essential for the maintenance of the correct salt and water balance at the surface of epithelial cells." (PMID 40566080, 2025). "A landmark 2024 study shows increased cellular senescence markers in cystic fibrosis bronchial epithelium across human samples, cell lines, and cystic fibrosis transmembrane conductance regulator (CFTR) knockout rat models." (PMID 41007626, 2025). "Cystic Fibrosis before the advent of the Cystic Fibrosis Transmembrane Conductance Regulator (CFTR) modulators was once considered a chronic, progressively worsening disease, the result of this view being that patients’ life planning was very limited." (PMID 40327240, 2025). "This article presents the clinical presentation and results of CFTR channel function assessment and personalized selection of CFTR modulators in monochorionic diamniotic twins with cystic fibrosis and the L467F;F508del/CFTRdele2,3 genotype." (PMID 41373889, 2025). "Since this weakest link was also the final posttranslational CFTR folding, its stability is essential for optimizing CFTR activity and cystic fibrosis treatment." (PMID 40831506, 2025). "Cystic fibrosis is an autosomal recessive genetic disorder that affects approximately 100,000 individuals globally and is caused by a mutation in the Cystic Fibrosis Transmembrane Conductance Regulator (CFTR) gene, located on the long arm of chromosome 7." (PMID 40648998, 2025). "The introduction of CFTR modulator therapy has been long-awaited by individuals with cystic fibrosis and their caregivers." (PMID 41303006, 2025). "In summary, cystic fibrosis is characterized by exacerbated oxidative stress and chronic inflammation due to CFTR malfunction." (PMID 40867576, 2025). "The introduction of CFTR modulators has dramatically shifted the clinical management of cystic fibrosis from a life-limiting pediatric condition to a chronic disease with broader health implications." (PMID 41154689, 2025). "This is particularly relevant for CFTR and the evaluation of therapeutic approaches for correction of the basic defect in cystic fibrosis." (PMID 40047394, 2025). "Cystic fibrosis is a rare, life-limiting autosomal recessive genetic disorder caused by mutations in the gene encoding the chloride-conducting transmembrane channel, known as CFTR, that regulates anion transport across multiple epithelia." (PMID 40806881, 2025).